MMP9 (matrix metallopeptidase 9)
Diseases named in the same sentence as MMP9 in open-access papers (continued):
Sharing a sentence is not in itself a finding about the gene and the disease.
tumor (continued). "However, studies correlating MMP-9 levels with tumor and edema volumes in patients are scarce." (PMID 41573658, 2025). "Notably, MMP9 expression was found to be significantly higher in macrophage‐enriched compartments compared to the epithelial‐enriched compartments, displaying a gradient pattern that varied with tumour differentiation." (PMID 40847563, 2025). "However, aberrant or sustained complement activity within the tumor microenvironment often drives pro-tumorigenic processes, including TAM polarization, angiogenesis, recruitment of immunosuppressive MDSCs, and MMP-9–mediated metastasis, highlighting its dual role in regulating tumor metabolism." (PMID 41200171, 2025). "Importantly, research has demonstrated that MMP9 released by bone marrow-derived neutrophils collaborates with other hematopoietic lineage cells, possibly by modulating the tumor microenvironment or extracellular matrix remodeling, to promote the initiation of squamous cell carcinoma." (PMID 40564191, 2025). "Moreover, MMP-9 abundance within NETs may further contribute to the dysfunctional behavior of NK cells, facilitating immune evasion by malignant tumor cells." (PMID 40365275, 2025). "Moreover, the tumor-promoting potential of DMSO-dHL-60 cells shown in current study may be driven by elevated production of angiogenic MMP-9 and ROS." (PMID 40920704, 2025). "Importantly, tumor cells secrete MMP-9, which contributes to angiogenesis and tumor growth." (PMID 41516122, 2025). "Furthermore, we show that the interaction between tumor unmatched CAFs and HNSCC cells in the tumor spheroids is associated with significant changes in the mRNA expression of CAF-specific markers and a significant increase in FMOD and MMP9 expression in the 3D coculture model." (PMID 38822309, 2024). "The MMP-9 levels can be increased in neoplastic disease and this could have affected the results." (PMID 38341543, 2024). "Interestingly, MMP-9 could exert proangiogenic activity by favoring the release of matrix-sequestered angiogenic factors in the early stages of tumor development." (PMID 38247872, 2024). "Additionally, CHI3L1 affects MMP-9, contributing to tumor invasion." (PMID 38177294, 2024). "Moreover, MMP-9 has been used to predict tumor recurrence and survival in patients with HCC." (PMID 38461536, 2024). "To evaluate whether melittin inhibits tumor cell invasion and metastasis by interfering with EMT progression, we examined the expression of EMT-associated proteins, including MMPs (MMP2, MMP9), E-cadherin, N-cadherin, Vimentin, and related regulatory protein, in both in vivo and in vitro models." (PMID 39519238, 2024). "Notably, 5-FU treatment, while reducing tumor bulk, left behind MMP9-positive dormant cells, which may later drive invasion and metastasis." (PMID 39664453, 2024). "Moreover, RSV could hinder neoplasm metastasis through lowering the expression of MMP9, which is simulated by tumor derivative factors." (PMID 39881868, 2024). "However, as the tumor metastasis evolves, these neutrophils transition to a pro-cancer phenotype characterized by a decline in IL-1β and heightened expression of MMP-9 expression, along with curtailed T cell activation, decreased production of cytokines, and diminished interferon γ signaling." (PMID 38243240, 2024). "Thus, our findings highlight the emerging complexity of the immune-associated angiogenic drivers in the tumor microenvironment, adding new elements to the already established TAN-derived proangiogenic factors including MMP-9, VEGF, FGF-2, and Bv8/S100 proteins (summarized in a recent review)." (PMID 38329810, 2024). "MMPs are upregulated in the tumor tissues and promote tissue colonization by metastatic cells; therefore, we asked whether the increased incidence of lung metastases observed in CD93–/– mice was associated with MMP9 upregulation." (PMID 38441970, 2024). "Moreover, reduced MMP-9 expression was confirmed in tumor sections by immunohistochemistry." (PMID 39335164, 2024).
tumor (continued). "Considering the whole process of angiogenesis in the RCC samples studied, the pathway associated with the actions of MMPs may be due to hsa-miR-15b-5p, hsa-miR-99b-5p, hsa-miR-181a-5p as they exert their role in their interactions as tumor suppressors with MMPs, especially with MMP-9 and MMP-2." (PMID 39062015, 2024). "Finally, VM structures provide vascular channels for neutrophil infiltration and activation, leading to their expression of arginase, CCL2, CXCR4, and MMP-9 to promote angiogenesis and evade anti-angiogenic therapy, collectively suggest a critical role of neutrophils for tumor angiogenesis." (PMID 38580870, 2024). "However, the non-immunological functions, such as invasion, metastasis, and adhesion to fibronectin of B7-H3 mediated by Jak2/Stat3/MMP-9 signaling, received great attention over its co-stimulatory or co-inhibitory effects on immune cells and the anti-tumor response in early studies." (PMID 37605389, 2024). "Besides, a study shows that in ccRCC, MMP9 can regulate tumor immunity." (PMID 38375034, 2024). "In addition to their effects on immune responses, MDSCs promote tumor development by secreting vascular endothelial growth factor (VEGF) and matrix metalloproteinase-9 (MMP9) to support tumor angiogenesis and expressing CXCR2 to promote the formation of pre-metastatic niche." (PMID 38609997, 2024). "Additionally, CHI3L1 affects MMP9, promoting tumor invasion and metastasis." (PMID 38177294, 2024). "Treatments targeting cancer may inadvertently enhance MMP9 activity, which, while aiming to suppress tumor growth, might also facilitate tumor spread and contribute to the deterioration of nerve health through mechanisms converging on MMP9’s multifunctionality." (PMID 39664453, 2024). "RNA-Seq of bulk tumor samples verified an enrichment of neutrophil-derived genes in combination-treated tumors, specifically, genes associated with pathological activation of neutrophils and MDSC-mediated suppressive function, such as S100a8/a9, Mmp9, and Arg1." (PMID 37988164, 2024). "Matrix metalloproteinase 9 (MMP-9), also known as type IV collagenase, gelatinase, or gelatinase B, plays a key role in the disruption of the blood–brain barrier and facilitates the release of local tumor growth factors associated with the promotion of angiogenesis." (PMID 39684754, 2024). "To further explore the pathway enrichment associated with the regulation of tumor immunity by MICA and MMP9, we performed GSEA using the all differentially expressed genes (FDR q-value < 0.05) obtained from the previous analyses in MICA+ HCC cells and MMP9+ macrophages." (PMID 38254761, 2024). "The researchers found that xenograft tumours from “double-hit” cell lines had increased MMP-2 and MMP-9 activity compared to tumours from “single-hit” cell lines, which could also account, in part, for the poor clinical outcome of HNSCC patients with the “double-hit” profile." (PMID 38203696, 2023). "In addition, CX3CL1 increased the secretion of platelet-derived factor 4 (PDF-4)/CXCL4 in macrophages and cooperated with MMP9 released by stromal cells to support tumor angiogenesis, which further accelerated the accumulation of monocytes from peripheral blood." (PMID 37968706, 2023). "Moreover, neutrophil MMP9 seems to be important for tumor progression." (PMID 37532996, 2023). "Therefore, SAL may exert anti-tumor effects by inhibiting the metastasis of EC cell lines through MMP9." (PMID 37644107, 2023). "Besides, the use of AMG-510 inhibited the expression level of MMP9, which could promote tumor metastasis through the PI3K/Akt pathway." (PMID 37284902, 2023). "Moreover, MMP-9 is essential for tumor invasion, metastasis, and angiogenesis." (PMID 37175435, 2023).
tumor (continued). "On the one hand, TANs may promote tumor occurrence by generating reactive oxygen species (ROS), releasing neutrophil elastase (NE) to accelerate tumor growth, secreting matrix metalloproteinase-9 (MMP-9) to induce angiogenesis, and forming NETs to facilitate tumor metastasis." (PMID 38204755, 2023). "MMP-9 could be a superior marker for determining lymph node involvement and tumor grade." (PMID 36938194, 2023). "MMP-9, as a member of the zinc-dependent endopeptidase family, could promote angiogenesis and cancer invasion by degrading type IV collagen of basal membrane near the tumor cell and extracellular matrix (ECM)." (PMID 36831707, 2023). "However, a higher degree of tumor malignancy correlated with a higher MMP-9 concentration in blood." (PMID 36979935, 2023). "Moreover, MMP9 expression was elevated in all tumor types compared to normal." (PMID 37732732, 2023). "CCR7 acts as a regulator in the migration of lymphocytes such as dendritic cells, T cells, and B cells to the lymph nodes, while MMP-9 degrades type IV collagen in tumor basement membranes, and extracellular matrix so that tumor cells may invade the surrounding tissues, then metastasis happens." (PMID 37600570, 2023). "In addition, other metastasis related genes (VEGFA, MMP-2 and MMP-9) decreased in tumor cells." (PMID 37853415, 2023). "Moreover, FABP5 is reported to accelerate tumor metastasis via regulation of MMP9 and MMP230." (PMID 37416772, 2023). "Grange and colleagues performed molecular characterization of microvesicles and identified specific mRNAs associated with tumor progression and metastasis, including VEGF, fibroblast growth factor-2 (FGF2), angiopoietin-1 (ANGPT1), ephrin-A3 (EFNA3), metalloproteinase (MMP)-2, and MMP9." (PMID 37762660, 2023). "Besides of ECM degradation, the binding of MMP-9 to α4β1 integrin induces several intracellular signaling to promote anti-apoptotic pathway and metastatic pathway in cancer cells, suggesting another pivotal mechanism of MMPs-induced tumor progression." (PMID 36906534, 2023). "Moreover, MMP2 and MMP9 can be affected by many tumor-related signaling pathways or cytokines." (PMID 37686118, 2023). "Moreover, Foxp3UP CD8 TILs exhibited increased expression of tissue-remodeling-related genes (Mmp9) and cell-adhesion-related genes (Itgb7, Itgae, and Itgam) that may have facilitated their mobility through the tumor stroma." (PMID 36045586, 2023). "In addition, it may be advantageous to (i) investigate the invasion- and angiogenesis-related molecules co-expressed with MMP-9, or (ii) develop strategies for inhibiting tumour-specific activators of MMP-9 instead of using direct inhibitors." (PMID 36765669, 2023). "Thus, the combination of VEGF inhibitors following TACE could, theoretically, regulate the expressions of cancer-promoting factors, e.g. VEGF and MMP-9, inhibit angiogenesis of tumors, and eventually reduce the possibility of tumor recurrence and metastasis." (PMID 37254146, 2023). "However, the HIF-1α inhibitor 2-ME2 abrogated the increase in VEGFA, MMP2, and MMP9 induced by GSTZ1 deficiency in orthotopic mouse models, revealing that inhibition of HIF-1α with 2-ME2 substantially reversed tumor growth, MVD, and progression in Gstz1-KO mice." (PMID 37906252, 2023). "TAM-induced MMP-2 and MMP-9 could promote angiogenesis and tumor vascularization." (PMID 37441589, 2023). "In addition, less tumor cells after i.v. injection invade the lung and survive in MMP9−/− mice." (PMID 37443052, 2023). "Therefore, MMP9 inhibition can reduce tumor invasion to surrounding tissues." (PMID 36560848, 2023). "Patients with uveal melanoma positive for MMP-2 and MMP-9 had a significantly higher incidence of metastatic disease and lower survival rate, indicating that proteolytic enzymes, such as MMPs, may play a central role in tumor spread." (PMID 36902129, 2023). "Finally, using flow cytometry, we showed that MMP9 was expressed by tumor-infiltrating neutrophils." (PMID 34980260, 2022).
tumor (continued). "The M2 type of macrophages releases matrix metalloproteinases MMP2 and MMP9 to degrade the extracellular matrix, which further stimulates the migration of vascular endothelium and induces angiogenesis and promotes the proliferation and metastasis of tumor cells." (PMID 35847897, 2022). "Therefore, MMP9 can serve as a biomarker for predicting tumor regression in TNBC." (PMID 36497286, 2022). "Interestingly, both MMP-2 and MMP-9 were reported to be overexpressed in equine sarcoid, suggesting that tumor progression could be the result of a mechanism responsible for proliferation and more collagen production." (PMID 36518899, 2022). "MMP2 and MMP9 proteins could rapidly hydrolyze the components of the intercellular matrix and the extracellular basement membrane, and they could destroy the natural barrier of tumor metastasis." (PMID 36144577, 2022). "In addition, a similar pattern of MMP-9 expression was described in bovine ocular squamous cell carcinomas, a tumor type attributed to different factors such as papillomavirus and herpesviruses, where an increased MMP-9 expression compared to the control group was demonstrated." (PMID 36518899, 2022). "Besides, animal experiments in vivo via oral administration of PEG/ZIF-8@HF further confirms that PEG/ZIF-8@HF shows anti-tumor effect by up-regulating the pro-apoptotic proteins caspase-3 and caspase-8, and down-regulating the migration-promoting invasion protein MMP-9." (PMID 35373691, 2022). "MMP-9 activated by chymase might also be involved in angiogenesis in the tumor environment." (PMID 36289761, 2022). "In addition, GNP can inhibit the expression of MMP-9, suggesting that GNP may have anti-tumor activity by regulating MMP-9." (PMID 35954126, 2022). "It remains to be determined if GBM resident immune cells such as macrophages that constitutively express ADAM8 could release EVs that might fail to suppress MMP9 expression in target cells, in conjunction with the possible tumor-promoting role of ADAM8 in macrophages." (PMID 35371977, 2022). "SLPI may also promote vascular invasion via induction of MMP-2 and MMP-9 production by tumor cells." (PMID 35842496, 2022). "Interestingly, high levels of MMP-9 detected in laryngeal cancer could play a critical role in the development of Treg cells, which have an ability to suppress the tumor-specific CD8+ T cells." (PMID 36230852, 2022). "The results indicate that AITC decreased the levels of myeloid cell lymphoma-1 (MCL-1), matrix metalloproteinase-9 (MMP-9), vascular endothelial growth factor (VEGF), and X-linked inhibitor of apoptosis (XIAP), and increased the expression of caspase-3, -8, and -9 in tumor sections." (PMID 36142326, 2022). "Neutrophils facilitate the tumor initiation through multiple mechanisms: they produce oxidative stress, can induce angiogenesis, attenuate the immune system (by the inhibition of macrophages’, DC’ and NK cells’ function), produce MMP9 and facilitate the extravasation of tumor cells." (PMID 35205842, 2022). "In addition, patients in S3 had high levels of the macrophage marker gene CD68 and EMT marker genes such as MMP2 and MMP9, indicating that these cells in the tumor microenvironment may play important roles in tumor progression." (PMID 35124891, 2022). "Their an mechanisim may be that they can promote the proliferation of T lymphocytes, secrete the cytokine interleukin-2, inhibits the secretion of interleukin-8, downregulates the protein expression of VEGF and MMP-9, restrain the formation of new blood vessels, and control tumor cell adhesion." (PMID 36438813, 2022). "Impressively, when analyzing MMP-9 activity, its activated form of 82 kDa was readily detectable in all fibropapilloma, whilst it was present at low to undetectable levels in the normal skin samples, in agreement with western blotting results, denoting a strong activity during tumor development." (PMID 36518899, 2022). "Factors such as MMP9 in NETs may also contribute to tumor angiogenesis." (PMID 36555469, 2022).
tumor (continued). "Moreover, PCP-Mn-DTA@GOx@1-MT also displayed the strongest migration and invasion suppression with coverage rates of 30.1% and 24.9%, respectively (p < 0.01), as further revealed by the expression and quantitative analysis of the tumor invasion-associated proteins (E-Cadherin, MMP2, and MMP9)." (PMID 35577812, 2022). "MMP9 can degrade and destroy types IV and V collagen and gelatin in the extracellular matrix near the tumor surface; subsequently, tumor cells can infiltrate the surrounding tissues through the disrupted basement membrane, eventually leading to tumor invasion and metastasis." (PMID 36575422, 2022). "Furthermore, several studies also revealed that the role of PRL-3 in metastasis is mediated by MMPs, and the combined detection of the expression of PRL-3 and MMP9 in CRC can more comprehensively evaluate tumor metastasis potential than using PRL-3 or MMP9 expression alone." (PMID 35574414, 2022). "Therefore, it was speculated that JM2 could inhibit the expression of MMP2 and MMP9 and consequently inhibited the migration and invasion of tumor cells." (PMID 35332127, 2022). "Some studies have shown that the high expression of MMP-9 leads to the enhancement of tumor invasion, which maybe because the effect on the transforming growth factor (TGF-β1) induced epithelial mesenchymal transition (EMT) process, which promotes the invasion and metastasis of cancer." (PMID 36246294, 2022). "TNF-α can induce EMT in tumor cells by inhibiting the expression of epithelial marker E-cadherin, upregulating the expression of mesenchymal markers such as vimentin, N-cadherin, and fibronectin, and activating matrix metalloproteinase-9 (MMP-9), thus enhancing tumor invasion and migration activity." (PMID 35965509, 2022). "However, their presence may contribute to tumor progression by releasing vascular endothelial growth factor to support MMP9 degradation of the ECM." (PMID 36591235, 2022). "Therefore, an increased expression of MMP9 by neutrophils within the tumor microenvironment may increase tumor progression and development." (PMID 35741003, 2022). "Therefore, GNP is likely to become an MMP-9 inhibitor that can effectively treat tumor metastasis." (PMID 35954126, 2022). "This suggests that MMP-9 may lead to poor prognosis by participating in tumor immune infiltration." (PMID 35178444, 2022). "Therefore, we speculate that PMN-MDSC-derived IL-1β may stimulate tumor cells to produce MMP-9 in micrometastatic regions, thereby leading to ECM remodeling and the establishment of a favorable microenvironment for tumor growth." (PMID 35805039, 2022). "Furthermore, our ELISA data indicated that the increased VEGFA, MMP2, and MMP-9 levels upon BATF2 downregulation were significantly impaired after AMD3100 injection, suggesting that these tumour-promoting cytokines associated with MDSCs were also blocked by AMD3100." (PMID 33452462, 2021). "However, we show that macrophages are responsive to RA and that treatment with RA induces increased activity of MMP-2 while decreasing activity of MMP-9, which may aid in tumor progression." (PMID 34572134, 2021). "Therefore, high expression of MMP-9 often means an enhanced ability of tumor invasion." (PMID 34122670, 2021). "Together with our previous data, the present results suggest that the blockade of MCP-1/CCR2 pathway by irbesartan reduces the accumulation of fibrocytes into the inflamed colon and might inhibit tumour progression through the reduction of Col I and MMP-9 production." (PMID 34620946, 2021). "MMP9 is an essential factor of selectively modulating the tumor microenvironment and promoting tumor cell development as an inducer of EMT 44, bringing to light that modulation of activity of SLPI may be therapeutically relevant in ovarian cancer, especially influencing metastasis." (PMID 34405003, 2021).